LDHA (lactate dehydrogenase A)
Diseases named in the same sentence as LDHA in open-access papers (continued):
Sharing a sentence is not in itself a finding about the gene and the disease.
gastric cancer (continued). "The upregulation of mitochondrial topoisomerase I (TOP1MT), observed in invasive cancer cells, increases both in vitro and in vivo expression of lactate dehydrogenase A (LDHA), which is associated with enhanced glycolysis and EMT in gastric cancer cells." (PMID 31027222, 2019). "In intestinal-type gastric cancer cell lines, silencing LDHa downregulates Zeb2 and the synergistic decrease of LDHa and Zeb2 decreased cancer invasion, metastasis and poor prognosis." (PMID 31849832, 2019). "Consequently, LDHA overexpression facilitates gastric cancer cell proliferation and migration, exerting detrimental effects on patients with gastric cancer." (PMID 40865948, 2025). "Notably, lactate dehydrogenase A succinylation at K222 has been shown to inhibit its degradation, promoting invasion and proliferation in gastric cancer." (PMID 38166693, 2024). "SNHG7 desensitizes gastric cancer cells to cisplatin via the miR-34a/LDHA-glycolysis axis." (PMID 38927012, 2024). "In this study, LDHA was used as the key regulatory target of lactylation, and it was revealed that the expression level of LDHA was proportional to the degree of lactylation in gastric cancer." (PMID 38041125, 2023). "Increases in LDHA levels in gastric cancer can increase lactylation levels." (PMID 38041125, 2023). "This is the first study to correlate GLUT3 and LDHA with lactatylation, which could be important for guiding subsequent studies on lactylation in gastric cancer." (PMID 38041125, 2023). "In addition, CPT1A succinylates lactate dehydrogenase A (LDHA) at K222 that leads to reduced LDHA degradation in gastric cancer and consequently promotes cell invasion." (PMID 36605449, 2022). "Recently it was found that miR-7 could target lactate dehydrogenase A (LDH-A) in gastric cancer cells, so its downregulation can influence glycolysis, cell proliferation and sensitivity to chemotherapy." (PMID 33806891, 2021). "In addition, LDHA, a key enzyme catalyzing the conversion of pyruvate to lactate, has been reported as a potential target for the treatment of gastric cancer." (PMID 34065602, 2021). "The LDHA inhibitor sodium oxamate is known to be an effective anticancer agent in many types of cancer, including breast, non–small cell lung, and gastric cancer." (PMID 30688660, 2019). "We found that, in gastric cancer cells, LDHA activity was significantly increased in SIRT3 overexpressing cells, whereas decreased in SIRT3 knockdown cells compared to NC or Scr control cells separately without detectable change in LDHA protein level in the stable transfectants." (PMID 26121691, 2015). "In addition, a study revealed that SIRT3 participated in the mitochondrial metabolic balance of gastric cancer and promoted deacetylation and activation of LDHA, thereby enhancing glycolysis and proliferation of gastric cancer, and was considered a cancer promoting factor." (PMID 40421455, 2025). "Furthermore, LDHA is required for the activation of mTOR in gastric cancer." (PMID 39394200, 2024). "However, the specific mechanisms and pathways responsible for the increases in LDHA expression and lactylation in gastric cancer remain unknown." (PMID 38041125, 2023). "For example, in gastric cancer (GC), circ-Donson binds to Mir-149-5p, while Mir-149-5p targets LDHA in GC." (PMID 36447119, 2023). "In addition, HAGLR sponges, miR-338-3p, could promote 5-Fu resistance in gastric cancer by targeting the LDHA-glycolysis pathway." (PMID 36979404, 2023). "Protein succinylation mediated by CPT1A has been demonstrated to promote the proliferation and invasion of gastric cancer (GC) by regulating LDHA succinylation." (PMID 36577755, 2022). "Thus, targeting glycolytic enzymes, including LDHA, with CA might be an alternative strategy for overcoming chemoresistance, especially in 5FU-resistant gastric cancer." (PMID 34065602, 2021).
gastric cancer (continued). "LDHA, which is a key glycolytic enzyme and catalyzes the interconversion of pyruvate and lactate, is widely overexpressed in a series of cancers including gastric cancer, and the high expression of LDHA in gastric cancer has been associated with shorter overall survival." (PMID 31904088, 2020). "In gastric cancer, CPT1A succinylates LDHA at K222, thereby inhibiting its degradation and promoting the proliferation and invasion of gastric cancer cells." (PMID 39781339, 2025). "In gastric cancer (GC), several key enzymes and transporters, namely ALDOA, GLUTs, LDHA, and PKM2, have been widely investigated as potential biomarkers." (PMID 41154605, 2025). "First, HMGB2 boosts the transcriptional activity of HIF-1α, leading to upregulation of glycolytic enzymes such as LDHA, PKM2, and HK2, which help gastric cancer cells sustain glycolysis under hypoxic conditions." (PMID 41220952, 2025). "Specifically, CagA expression is significantly elevated in 5-FU–resistant gastric cancer cells, along with increased expression of glycolytic enzymes such as hexokinase 2 (HK2) and lactate dehydrogenase A (LDHA)." (PMID 41220952, 2025). "Furthermore, LDHA was found to be hypersuccinylated at K222 catalyzed by CPT1A in gastric cancer (GC) to promote GC cell proliferation, invasion, and migration." (PMID 38315203, 2024). "In gastric cancer (GC), CPT1A-mediated LDHA-K222succ reduces its binding to SQSTM1 and inhibits the degradation of LDHA, as well as promotes GC invasion and proliferation." (PMID 38882606, 2024). "For example, in fluoropyrimidine 5-fluorouracil (5-FU) resistant colorectal and gastric cancers, inhibiting PKM2-mediated and LDHA-mediated glycolysis significantly enhanced the cytotoxicity of 5-FU." (PMID 37024456, 2023). "On the other hand, knockdown of USP4 in gastric cancer cells led to a decrease in the expression of GLUT1 and LDHA." (PMID 37624791, 2023). "Several studies have suggested that 18F-FDG PET/CT, a noninvasive molecular imaging technique to detect malignant tumors, can predict gene expression status, such as LDHA in lung cancer and HER2 in gastric cancer." (PMID 36644641, 2022). "In comparison with the gastric cancer cell line, SNU620, 5-FU-induced SNU620/5-FU drug-resistant cells exhibit stronger glycolytic characteristics, higher levels of LDHA expression, higher extracellular acidification, and growth rates." (PMID 36438836, 2022). "It has been reported that SIRT3 can promote lactate dehydrogenase A (LDHA) deacetylation and activation to enhance glycolysis and proliferation in gastric cancer." (PMID 35571098, 2022). "Lysine-222 succinylation is increased in gastric cancer, and LDHA lysine-222 succinylation, catalyzed by CPT1A via the stabilization of LDHA, promotes GC invasion and proliferation." (PMID 35004688, 2021). "Taken together, resistant gastric cancer SNU620/5FU cells have glycolytic phenotypes, including elevated lactate production and higher LDHA expression than those in parental SNU620 cells." (PMID 34065602, 2021). "We then verified the protein profile results by western blotting assay and found that gastric cancer exosomes contained key enzymes of the glycolysis pathway, such as PKM2, LDHA, and PFKP." (PMID 33731686, 2021). "Additionally, the levels of LDHA, L-lactyl, H3K9, H3K18, and H3K56 significantly decreased after GLUT3 knockdown, indicating that GLUT3 affects lactylation in gastric cancer cells." (PMID 38041125, 2023). "Through research on stomach cancer, it was discovered that baicalin inhibits the expression of three important glycolysis enzymes, HK2, LDHA, and PDK, reducing the rate of glycolysis and reversing the hypoxia-induced sensitivity of AGS cells to pentafluorouracil." (PMID 36339566, 2022). "High levels of LDHA were confirmed also in gastric cancer (HER2 positive tumors have a significantly higher LDHA level than HER2 negative), and nasopharyngeal carcinoma." (PMID 31035592, 2019).
gastric cancer (continued). "Similarly, in gastric carcinoma (GC) LDHA overexpression is transcriptionally regulated by FOXM1; overexpressed LDHA resulted in a glycolytic phenotype of cancer cells and promoted GC progression." (PMID 31146503, 2019). "In clinical studies of gastric cancer (GC), NSCLC, and melanoma, elevated expression of glycolysis-related molecules lactate dehydrogenase A and oncogene c-Myc (MYC) correlated with resistance to PD-1 blockade." (PMID 41281945, 2025). "Oxamate, a pyruvate-competitive LDHA inhibitor, has been shown to inhibit the proliferation of gastric cancer cells; however, in vivo experiments could not be conducted due to its high effective dose." (PMID 39596288, 2024). "LDHA levels were not significantly different between patients with early-stage gastric cancer (stages I–II) but were significantly elevated in patients with late-stage gastric cancer (stages III–IV)." (PMID 38041125, 2023). "In addition, as a key protein regulating anaerobic glycolysis, lactate dehydrogenase A (LDHA) could be deacetylated and activated by SIRT3 to promote glycolysis and increase ATP production in gastric cancer cells." (PMID 35832551, 2022). "Again, the regulation of LDHA by c‐Myc is not straightforward; studies in gastric cancer suggest that LDHA may be involved in a negative feedback loop, as inhibition of LDHA increases c‐Myc expression." (PMID 26269128, 2016).
lung carcinoma (73 papers, 2014 to 2026). "LDHA is abnormally highly expressed in many cancers, including lung cancer, and is associated with malignant progression, is a biomarker for cancer diagnosis and prognosis." (PMID 36404333, 2022). "Our results showed the A549 cells with Kras mutation was less sensitive to the combination of LDHA inhibition and radiotherapy than H1975, reflecting the heterogeneity of lung cancer." (PMID 33902615, 2021). "Kaplan–Meier plots demonstrate that the high levels of HK2, SLC2A1 (GLUT1), LDHA, and HIF1a expression were associated with poor survival of lung cancer patients." (PMID 34692483, 2021). "For example, LDHA is upregulated in lung cancers with poor survival and is associated with increased glycolytic flux." (PMID 32411371, 2020). "High LDHA levels have been linked to poor prognosis in many cancers, including liver and lung cancer." (PMID 29541451, 2018). "We have recently shown that deletion of lactate dehydrogenase A (LDH-A) and subsequently lactate in myeloid cells leads to regression of lung cancer and is associated with stronger anti-cancer immune responses." (PMID 30151352, 2018). "Taken together, these results demonstrate that the loss of DSTYK activates Wnt/β-catenin/LDHA signaling to promote the tumorigenesis of lung cancer and that DSTYK may be a therapeutic target." (PMID 34853310, 2021). "Analysis of human lung cancer samples has revealed a strong inverse correlation between LDHA levels and miR-449a expression, suggesting that miR-449a suppresses LDHA production to reduce glycolytic rates." (PMID 40303296, 2025). "It has been shown that upregulation of LDHA expression promotes the proliferation and migration of lung cancer cells and reduces the survival rate of lung cancer patients." (PMID 40880642, 2025). "Many studies have documented elevated oxalate in tumor tissues and blood of lung cancer, and inhibition of LDHA expression can effectively reduce oxalate production." (PMID 38567154, 2024). "To validate the accuracy of the analysis, we improved the transwell assay and scratch test of LDHA in tumor cells, and found that high LDHA expression promoted the proliferation, migration and invasion of lung cancer cell line NCI-H441." (PMID 38709280, 2024). "Recent work elucidates the up-regulation of PD-L1 in glucose-stimulated lung cancer cells mediated by GPR81 through lactate dehydrogenase A (LDHA)." (PMID 36875841, 2023). "Consistent with our results, other PSMC signature-related genes, including LDHA, SEC61G, PLEK2, and C1QTNF6, have been shown to be risk genes in lung cancer in vitro, mediating the development, growth, and metastasis of lung cancer." (PMID 36699466, 2022). "LncRNA CRYBG3 potentiated glycolysis via interaction with lactate dehydrogenase A (LDHA) in lung cancer." (PMID 36313695, 2022). "This positive feedback promotes c-Myc-mediated transcriptional regulation of HK2 and LDHA, accelerating the aerobic glycolysis of lung cancer." (PMID 35927226, 2022). "Bioinformatic analysis revealed the synergistic effect between the Set7/9 and either HIF1A, HK2, GLUT1, or LDHA expression levels on the survival outcome of lung cancer patients." (PMID 34692483, 2021). "The expression level of LDHA has been negatively correlated with the survival of lung cancer patients." (PMID 34853310, 2021). "The mRNA expression levels of CAT, ENTPD2 and LDHA were also investigated in 6 lung cancer cell lines (A549, H460, H1299, H1975, PC9, Lewis), 16HBE as control." (PMID 33858449, 2021). "Bioinformatic analysis has shown a synergistic impact of Set7/9 together with either GLUT1, HIF1A, HK2, or LDHA on the survival of lung cancer patients." (PMID 34692483, 2021). "In a murine model of KrasG12D-driven lung cancer, pharmaceutical LDHA inhibition also inhibited both tumor progression and regression." (PMID 30832375, 2019).
lung carcinoma (continued). "In this study, we provide the first evidence that SUN2 plays a tumor suppressor role by suppressing the expression of GLUT1 and LDHA to inhibit the Warburg effect in lung cancer." (PMID 26658802, 2015). "Also, LDHA knockdown in lung cancer cells resulted in MET induction through decreased E-cadherin and increased vimentin, N-cadherin, Snail, and ZEB1 expression." (PMID 40507273, 2025). "Furthermore, it was confirmed that knockdown of LDHA reduced proliferation and migration ability of lung cancer cells." (PMID 38709280, 2024). "In addition, studies have shown that inhibition of LDHA expression can significantly inhibit cell proliferation, colony formation and migration in lung cancer patients, and enhance their sensitivity to conventional chemotherapy and radiotherapy." (PMID 36447119, 2023). "High-risk genes in the model, including ANGPTL4, LDHA, and NPAS2, have been reported to promote angiogenesis, glycolysis, drug tolerance, the invasive and migratory potential, and cell cycle and apoptosis in lung cancer patients or cell lines." (PMID 35295857, 2022). "LDHA has also been shown to mediate the functions of many oncogenes in lung cancer." (PMID 34853310, 2021). "Multiple studies have demonstrated the roles of LDHA in the progression of lung cancer." (PMID 34853310, 2021). "Therefore, the effects of SGH on the glucose consumption, lactate production, and expression levels of the glycolytic regulators HK2, PKM2, and LDHA in lung cancer cells were investigated." (PMID 33572615, 2021). "We sought to investigate whether there are correlations between the expression levels of glycolytic genes HIF1A, GLUT1, HK2, and LDHA, in lung cancer patients and the rates of the patients’ survival." (PMID 34692483, 2021). "Overexpression of lncRNA-IGFBP4–1 via targeting HK2/PDK1/LDHA could affect energy metabolism and promote lung cancer progression." (PMID 33123468, 2020). "Importantly, c-Myc knockdown in ZNF322A-silenced lung cancer cells reversed the suppression of LDHA and HK2 expression while reducing the upregulation of PGC1A." (PMID 30258097, 2019). "Moreover, blocking lactate production by specifically targeting LDHA leads to differentiation of glioblastoma TICs and to reduced lung cancer tumorigenesis." (PMID 27589845, 2016). "We and others have previously shown in cholangiocarcinoma and lung cancer, respectively, that tumour-associated angiogenesis is induced by PKM2 and LDHA, which could be another contributing factor to poor prognosis." (PMID 26989901, 2016). "To address the issue of whether SUN2 regulates the Warburg effect, we investigated the effect of SUN2 on GLUT1 and LDHA expression in lung cancer cells." (PMID 26658802, 2015). "As previous studies have shown that CDDP treatment inhibits LDHA expression in lung cancer cells, in the present study investigated whether LDHA is downregulated by CDDP treatments in oral squamous cancer cells." (PMID 25789051, 2015). "Besides, SH2B1 knockout led to downregulation of GLUT1, PDK1, and LDHA in lung cancer cells." (PMID 41410190, 2025). "Therefore, LDHA is expected to be a promising prognostic indicator for lung cancer treatment." (PMID 36447119, 2023). "In summary, the present study reveals that elevated AKR1B10 enhances glycolysis through regulation of LDHA and the resulting elevated lactate promotes transcriptional activation of the cell cycle-related gene CCNB1 by histone lactylation, inhibiting the susceptibility of lung cancer BM cells to PEM." (PMID 37587486, 2023). "Thus, optimization of GLUT1 (BAY and DRB-18) or LDHA inhibitors may offer novel therapeutic strategies for treating lung cancer." (PMID 30832375, 2019). "In brain metastases of lung cancer, AKR1B10 upregulates H3K18 lactylation, suppresses LDHA expression, and induces resistance to PEM." (PMID 40843350, 2025). "Immunohistochemical staining was utilized for identifying the expression of LDHA, CDKN3, SHC1, and BTK in 127 lung cancer samples." (PMID 40182622, 2025).